RNU6-1299P (RNA, U6 small nuclear 1299, pseudogene)
Gene: Small nuclear RNA gene on chromosome 6 (107,133,071 to 107,133,170, forward strand). Ensembl gene ENSG00000252125.
Homologues: Orthologues: chimpanzee U6 (98% identical), macaque U6 (95% identical), dog U6 (71% identical), guinea pig U6 (68% identical), guinea pig U6 (67% identical), rabbit U6 (62% identical), mouse Gm25269 (61% identical), rat LOC120096466 (60% identical). Paralogues in human: RNU6-1209P (86% identical), RNU6-183P (83% identical), RNU6-204P (83% identical), RNU6-1311P (82% identical), RNU6-560P (82% identical), RNU6-862P (82% identical), RNU6-1091P (81% identical), RNU6-11P (81% identical), RNU6-130P (81% identical), RNU6-161P (81% identical), RNU6-268P (81% identical), RNU6-370P (81% identical), and 1286 more.